SCRN1 (secernin 1)
Diseases named in the same sentence as SCRN1 in open-access papers (continued):
Sharing a sentence is not in itself a finding about the gene and the disease.
tumor (11 papers, 2015 to 2023). "The majority of previous research studying SCRN1 has examined its role in cancer, where it was found to be overexpressed in a variety of cancers and determined to be a tumor-associated protein that correlated with tumor development and poor prognosis." (PMID 31796108, 2019). "Our previous work identified SCRN1 as a tumor-associated gene by bioinformatics analysis of transcriptomes." (PMID 25814779, 2015). "We also revealed that overexpression of SCRN1 was significantly associated with the tumor development and poor prognosis." (PMID 25814779, 2015). "To further confirm that SCRN1 functions a tumor promoter in OSCC by regulating the TGF-β/Smad3 pathway, we next assessed the effects of TGF-β on OSCC cell proliferation, migration and invasion." (PMID 37691034, 2023). "Our results demonstrated that SCRN1 promotes tumor invasion and migration by activating the TGF-β signaling pathway." (PMID 37691034, 2023). "SCRN1 accelerates tumor progression by the regulation of exocytosis of matrix metalloproteinase-2/9 (MMP-2/9), while RSPO3 is an oncogenic driver that causes CRC and extensive crypt hyperplasia, concomitantly stimulating stem cells and supportive niche cells." (PMID 37228491, 2023). "We found that high SCRN1 expression was correlated with the tumor stage, nodal stage, and clinical TNM stage." (PMID 37691034, 2023). "The CTL clones stimulated by SCRN1 were able to recognize tumor cells that expressed the natural SCRN1 protein endogenously." (PMID 37398650, 2023). "In summary, our data provided evidence, for the first time, that high expression of SCRN1 is correlated with the tumor stage, nodal stage, and clinical TNM stage." (PMID 37691034, 2023). "Relative expression of the SCRN1 gene and miR-148a between tumor and normal tissues indicated that this gene in the tumor sample was overexpressed (p < 0.001), and miRNA-148a was decreased in the tumor tissue compared to normal tissue (p < 0.001)." (PMID 35330456, 2022). "A proteomics analysis of tumor specimens collected from 13 SS patients, identified SCRN1 as positive prognostic factor with significantly higher expression among patients who were alive and disease free for at least 5 years." (PMID 28191313, 2017). "The PIN showed higher secernin-1 expression levels than the tumors but lower secernin-1 expression than the tumor-free tissues (P < 0.01)." (PMID 25667921, 2015). "SCRN1 expression was low in normal tissues and low and high in tumor tissues." (PMID 37691034, 2023). "Additionally, the drug combination upregulated PINK1, IRF1, PPP1R15A, CRABP2, SCRN1, LIMA1, and TGFBI; all genes associated with tumor suppression functions in PCa." (PMID 29545934, 2018). "Importantly, we found novel protein changes including high levels of oncogenic proteins such as R-Spondin 3 (RSPO3) and secernin 1 (SCRN1) as well as low levels of tumor suppressors such as Ret proto-oncogene (RET) and Rho guanine nucleotide exchange factor 12 (ARHGEF12) in CRC patients." (PMID 37228491, 2023). "Interestingly, several oncogenic proteins were elevated in plasma, such as SCRN1 and RSPO3, whereas previous studies determine their overexpression in CRC tumor tissue." (PMID 37228491, 2023). "TGF‐β treatment reversed the decreases in the proliferation, invasion and migration of tumor cells induced by SCRN1 knockdown as well as the decrease in p-SMad3 expression in OSCC cell lines, suggesting that SCRN1 acts promotes OSCC by modulating the TGF‐β/Smad3 pathway." (PMID 37691034, 2023). "Experiments in vitro validated that SCRN1 may promote cancer cell proliferation and secretion of matrix metalloproteinase-2/9 (MMP-2/9) proteins to accelerate tumor progression." (PMID 25814779, 2015). "Moreover, we reported that SCRN1 promotes colon cell proliferation and enhances the secretion of MMP-2/9 to accelerate cancer cell invasion and tumor metastasis." (PMID 25814779, 2015).
tumor (continued). "Further analysis of SCRN1 expression in 45 SS tumor specimens revealed a 5-year survival rate was 77.6 and 21.8% for patients with secernin-1 positive and negative primary tumors, respectively (p = 0.0015), and significantly associated with metastatic outcomes." (PMID 28191313, 2017). "qPCR quantification of the relative expression of the five candidate genes LOXL1, SCRN1, VAMP5, SERPINB1, and TMSB4X in cryopreserved tumor tissues from validation set 1 was correlated to the CSIs measured in the corresponding fresh tissue samples of the same tumor lesions." (PMID 26799424, 2016). "Taking the SCRN1 function as a regulator of exocytosis in other cell types into consideration, we hypothesized that SCRN1 may enhance the secretion of MMP-2/9 to promote cancer cell invasion and tumor metastasis." (PMID 25814779, 2015). "Notably, some of the tumor glands of the immunohistochemically analyzed tumor sample set in the explorative phase showed a weak secernin-1 expression (data not shown)." (PMID 25667921, 2015).
cancer (8 papers, 2010 to 2025). A tumor composed of atypical neoplastic, often pleomorphic cells that invade other tissues. "Up-regulated Guanine nucleotide-binding protein G(i) subunit alpha-1, Secernin-1, Guanine nucleotide-binding protein G(i) subunit alpha-2 have all been associated with cell division and cancer." (PMID 27082425, 2016). "SCRN1 brown staining was mainly observed in the cytoplasm of colon epithelial, mesenchymal, and cancer cells." (PMID 25814779, 2015). "Secernin 1 has dipeptidase activity and has been demonstrated to play a role in exocytosis; it has been shown to be overexpressed in certain types of cancer and has also been suggested as a potential neurotoxicologically relevant target." (PMID 20069063, 2010). "Since accumulating studies have confirmed that TGF-β/Smad3 signaling plays extensive regulatory roles in the development and progression of multiple types of cancers, we next conducted Western blot assays to assess the effects of SCRN1 knockdown on the activity of TGF-β/Smad3 signaling." (PMID 37691034, 2023).
neurodegenerative disease (2 papers, 2019 to 2023). A disorder of the central nervous system characterized by gradual and progressive loss of neural tissue and neurologic function. "Here, we have performed a comprehensive immunohistochemistry study to characterize SCRN1 throughout the progression of AD and in a range of other neurodegenerative diseases." (PMID 31796108, 2019). "Therefore, we performed a comprehensive study of SCRN1 distribution in neurodegenerative diseases." (PMID 31796108, 2019).
SCRN1 also shares sentences with these, for which no sentence is quoted: Barrett esophagus (2 papers); Corticobasal Degeneration (2); Down syndrome (2); melanoma (2); progressive supranuclear palsy (2); amyloidosis (1); atherosclerosis (1); breast carcinoma (1); depression (1); gastrointestinal carcinomas (1); hemorrhagic stroke (1); inflammatory bowel disease (1); oral squamous cell carcinomas (1); Pick disease (1); prostatitis (1).